SPI1 (Spi-1 proto-oncogene)
Diseases named in the same sentence as SPI1 in open-access papers (continued):
Sharing a sentence is not in itself a finding about the gene and the disease.
renal carcinoma (1 paper, 2025). A carcinoma arising from the epithelium of the renal parenchyma or the renal pelvis. "We also performed western blot experiments on four renal cancer tumors to analyse the differential high expression of SPI1." (PMID 41372608, 2025). "Furthermore, we validated that knockdown of SPI1 combined with treatment erastin promotes renal cancer ferroptosis, elaborating on the mechanism that SPI1 interacts with EZH2 to mediate the transcriptional repression of ACSL4 targets by H3K27me3." (PMID 41372608, 2025). "Knockdown of SPI1 induces ferroptosis in ccRCC may be caused by restoring the expression of ACSL4, a downstream target of SPI1 within renal cancer." (PMID 41372608, 2025). "In addition, we utilized clinical sample analysis to identify differential expression of SPI1 and ACSL4 in renal cancer, consistent with the TCGA database." (PMID 41372608, 2025). "The correlation between SPI1 and ACSL4 was studied in renal cancer cell lines and tissue samples." (PMID 41372608, 2025).
renal cell carcinoma (1 paper, 2025). "In this study, we demonstrate that SPI1 is differentially overexpressed in renal cell carcinoma and associated with unfavorable prognosis." (PMID 41372608, 2025). "Although the role of SPI1 in renal cell carcinoma is recognized, its relationship with ferroptosis remains unclear." (PMID 41372608, 2025). "Thus, SPI1 knockdown synergizes with erastin to promote lipid peroxidation and ferroptosis, suggesting that targeting SPI1 may represent a promising therapeutic strategy for renal cell carcinoma." (PMID 41372608, 2025).
sarcoidosis (1 paper, 2022). Sarcoidosis is a multisystemic disorder of unknown cause characterized by the formation of immune granulomas in involved organs. "In a prior gene co-expression analyses of peripheral blood and cutaneous lesions we noted that transcription factors, such as ETS1, IKZF3, LEF1, MYC, RORA, and SPI1 (PU.1), may be central players in aberrant processes associated with sarcoidosis." (PMID 36311769, 2022). "However, some UIC STAR cohort key determinant genes, such as ATP6V0D1, FTH1, G6PD, HCK, and SPI1 have been previously associated with sarcoidosis in other studies." (PMID 36311769, 2022). "Furthermore, SPI1, which was significantly over-expressed in the ACCESS cohort and demonstrated the greatest magnitude of transcriptional targeting change in MAM, was identified in our prior work as a hub gene in a sarcoidosis co-expression network." (PMID 36311769, 2022).
sarcopenia (1 paper, 2022). Progressive decline in muscle mass due to aging which results in decreased functional capacity of muscles. "Together, these data show that myeloid cell‐specific mutation of Spi1 prevented sarcopenia in mice between 12 and 22 months old." (PMID 36098370, 2022). "In our investigation, we show that the targeted mutation of the transcription factor Spi1 in myeloid cells, causes a selective reduction in the activation of intramuscular macrophages to an M2‐biased phenotype and that leads to reductions in sarcopenia and fibrosis during muscle aging." (PMID 36098370, 2022).
squamous cell carcinoma (1 paper, 2021). A carcinoma arising from squamous epithelial cells. "The expression of SPI1 in NSCLCs has been reported, and increased number of PU.1+ cells is correlated with favorable prognosis of adenocarcinoma and poor prognosis of squamous cell carcinoma." (PMID 34293829, 2021).
tuberous sclerosis complex (1 paper, 2021). "Using RNA sequencing data from surgically resected tubers from tuberous sclerosis complex (TSC) patients and tissue from a tsc2−/− zebrafish knockout model we identified the transcription factor SPI1/PU.1 to be upregulated and its targets to be enriched among the differentially expressed genes." (PMID 33786950, 2021).
Wilms tumor (1 paper, 2008). An embryonal neoplasm characterized by the presence of epithelial, mesenchymal, and blastema components. "Important for their relation to Wilm's Tumor, several of these TFs have previously been implicated in cancer (NANOG, GLI1, E2F1, POU5F1/OCT4, SPI-1, YY-1, GATA1, and C/EBP-β)." (PMID 18564415, 2008).
infection (238 papers, 2007 to 2026). The state of being infected such as from the introduction of a foreign agent such as serum, vaccine, antigenic substance or organism. "Nevertheless, the majority of Salmonella are intracellular in the bloodstream, which is a phase of infection governed by virulence effectors delivered by T3SSs encoded by SPI-1 and SPI-2." (PMID 41326716, 2026). "During the initial phase of infection, Salmonella invades the intestinal epithelial cells using SPI-1-encoded effectors." (PMID 39462402, 2024). "SPI-1 is associated with target cell invasion during the infection initiation stage, whereas SPI-2 affects a broad range of systemic infection functions." (PMID 38563109, 2024). "The injectisome encoded on Salmonella pathogenicity island-1 (SPI-1) and the bacterial flagellum are two important virulence factors that are required by Salmonella Typhimurium to establish an infection in the host’s intestine." (PMID 37315106, 2023). "Both the bacterial flagellum and the evolutionary related injectisome encoded on the Salmonella pathogenicity island 1 (SPI-1) play crucial roles during the infection cycle of Salmonella species." (PMID 37315106, 2023). "The SPI-1-encoded injectisome is involved in the initial step of infection, where it translocates effector proteins into cells of the intestinal epithelium resulting in actin polymerization and remodelling." (PMID 37315106, 2023). "Identification of this lineage follows the previous detection of another lineage over-represented in swine compared with humans which carries a loss-of-function mutation in hilD, the major SPI-1 regulator, responsible for reduced infection of human cells." (PMID 37800927, 2023). "In the case of the adhesin SIIE, some studies show that the infection of host organisms by Salmonella involves the cooperative activity of the Salmonella pathogenicity island 1 (SPI1)-encoded type III secretion system (T3SS) and SIIE." (PMID 36140009, 2022). "Salmonella enterica serovar Typhimurium initiates infection by invading intestinal epithelial cells using a type III secretion system encoded within Salmonella pathogenicity island 1 (SPI-1)." (PMID 33593291, 2021). "It initiates infection by invading intestinal epithelial cells using a type III secretion system encoded within Salmonella pathogenicity island 1 (SPI-1)." (PMID 33593291, 2021). "KDM6B recruitment upon infection exhibited an associated loss of overall H3K27me3 in host cells and was Salmonella SPI1 effectors coordinated." (PMID 34696686, 2021). "Considering each mouse model separately, we can conclude ARHGEF26 plays a critical, multifaceted role in enabling S. Typhimurium to utilize the SPI-1 secretion system to cause disease in both models of murine infection." (PMID 34242364, 2021). "SPI-1 encoded proteins are also involved in the modulation of the host immune response during infection, reducing the stimulation of proinflammatory cytokines." (PMID 33228065, 2020). "Its mode of infection is basically characterized by its two main pathogenicity islands, SPI-1, and SPI-2 encoding the complex Type III secretion systems, TTSS-1, and TTSS-2, respectively." (PMID 32116124, 2020). "Our previous study showed that, in ROD9 (or as it is referred, SPI-19) island of S. Enteritidis, a gene SEN1005 encoding a hypothetical protein contributed to the infection profile by altering SPI-1 and other virulence-related genes expression." (PMID 32116124, 2020). "During the infection process, Salmonella relies on the expression of genes encoded on SPI-1 for epithelial cell invasion." (PMID 29879120, 2018). "Although numerous studies demonstrate a role of T3SS in host infection, recent studies using bovine, chicken, murine, and human models to determine the function of SPI1 suggest Salmonella can cause infection in a manner independent of T3SS." (PMID 28381209, 2017).
infection (continued). "SPI1 encodes a type III secretion system (T3SS) required for invasion of host gut epithelial cells in the early stages of infection." (PMID 28553268, 2017). "During infection, Salmonella invades epithelial cells lining the small intestine, mediated by Salmonella Pathogenicity Island 1 (SPI1), encoding a type 3 secretion system (T3SS)." (PMID 26039089, 2015). "Spontaneous SPI-1 mutations are thought to arise throughout host infection generating a subpopulation of “avirulent defectors” that propagate much faster than their TTSS-positive predecessors." (PMID 25375226, 2014). "A distinct T3SS, encoded by SPI-1, was already known to be essential for infection of mice via the oral route." (PMID 23637626, 2013). "The SPI-1 encoded type three-secretion system and flagella are important for rapid host cell death by pyroptosis seen after cell infection with S. Typhimurium." (PMID 23530934, 2013). "Some SPI-1 genes were up-regulated at multiple times post-infection and in both mutants, such as sicA, a gene encoding a complex chaperone protein required for Salmonella entry into host cells." (PMID 23442379, 2013). "Although numerous studies demonstrate a role of T3SS-1 in host infection, recent evidence from bovine, chicken, and murine models suggests that S. Typhimurium and other serotypes can also cause infection in a SPI-1-independent manner." (PMID 23170225, 2012). "The T3SS considered to be necessary for epithelial cell invasion is encoded on Salmonella Pathogenicity Island-1 (SPI-1), a large region of the Salmonella genome that contains numerous genes involved in pathogenesis and infection." (PMID 21206750, 2010). "SPI-1 is known to be involved in the intestinal phase/initial invasion of an infection, and hfq has recently been shown to affect the regulation of hilA, which is an important regulator of virulence genes encoded in SPI-1." (PMID 18986519, 2008). "This was complemented by invasion-related genes (invA-J, sipA-D, sptP, orgA, and prgH-K), predominantly encoded within SPI-1, which facilitate the incursion of host cells and the early stages of infection through their role in the Type III Secretion System (T3SS-1)." (PMID 40293991, 2025). "Remarkably, we see significant transcriptional induction of SPI-1 genes upon contact with macrophages, particularly those encoding structural components such as PrgI, PrgJ and PrgK, as early as 5–15 min post infection, aligning with the timeframe of the initial Salmonella–macrophage interaction." (PMID 41188240, 2025). "This phenotype corresponds with our previous observations of heightened invasiveness linked to a 10-nucleotide sanA mutation, reflects a link between sanA expression and infection dynamics, and suggests an association with SPI-1, which is a crucial factor responsible for Salmonella invasion." (PMID 40304475, 2025). "It is thus tempting to speculate that Salmonella induces both the SPI-1 encoded injectisome and several adhesin systems during the initial stage of infection in order to enhance binding of the bacteria to epithelial cells." (PMID 37315106, 2023). "Prior to infection, S.Tm injects a cocktail of effector proteins via the SPI-1 encoded T3SS into the cytoplasm, which results in membrane ruffling and subsequent invasion of the pathogen into an intracellular membranous compartment termed the Salmonella-containing vacuole (SCV)." (PMID 36902088, 2023). "As a potential proteinaceous mediator of PMN apoptosis had previously been described in the literature as being released by pathogenic bacteria during infection, we next examined the potential roles of SipA and SPI-1 in the induction of caspase-3 activity in PMNs." (PMID 28630067, 2017). "The intestinal phase of infection by S. Typhimurium includes internalization in epithelial intestinal cells mediated by the action of a type III protein secretion system (T3SS) encoded in the Salmonella Pathogenicity Island 1 (SPI-1)." (PMID 27145267, 2016).
infection (continued). "Combining the results of ChIP-seq, RNA-seq, real-time PCR (RT-PCR), mutation, and cell infection experiments, we showed that Fis influences the expression of 63 of the 94 SPI-1 and SPI-2 genes, which are responsible for the invasion and intracellular replication of LT2." (PMID 23717649, 2013). "The fact that mutations in SPI-1 or SPI-2 genes dampened neutrophil recruitment during infection could be simply a consequence of reduced pathogen load in the gastrointestinal tract." (PMID 23155475, 2012). "For infection of animal cells, S. Typhimurium uses two different T3SSs, encoded by SPI-1 and SPI-2." (PMID 21915285, 2011). "Moreover, it was shown that the severity and role of SPI-1 and 2 to cause infection by Salmonella Typhimurium depends on the host species, which further complicates data extrapolation to the human condition." (PMID 21206750, 2010). "Surprisingly, in addition to SPI2, the invasion-associated SPI1 pathogenicity island and the genes involved in flagellar biosynthesis were expressed inside epithelial cells at later stages of the infection, while they were constantly downregulated in macrophage-like cells." (PMID 18031307, 2008). "Additionally we show that only a small minority of Salmonellae are intracellular in the cecal epithelium of both infected animal models, and while SPI-1 is important for successful infection in the murine model, it is important for association with the cecal epithelium of 1-week-old chicks." (PMID 18922185, 2008). "While mgtC is in SPI3, and hilA primarily regulates expression of SPI1 genes during early infection, their co-existence has been reported to enhance systemic infection." (PMID 41596787, 2026). "The folding of the Salmonella chromosome in SPI-1 silent populations is conserved in exponentially growing cells and in other infection relevant conditions in which SPI-1 is bistably expressed." (PMID 41507177, 2026). "Through time-resolved parallel transcriptomic and translatomic studies of macrophage infection, we reveal SPI-1 injectisome-dependent infection of macrophages triggers rapid translation of transcription factors, including Early Growth Response 1 (EGR1)." (PMID 41188240, 2025). "Injectisome-independent internalization was assayed through infection with mutant Salmonella unable to assemble the injectisome needle, generated by knockout of the SPI-1 inner-rod protein PrgJ35 (ΔprgJ) and referred to as the injectisome mutant hereafter." (PMID 41188240, 2025). "Upon encountering host macrophages, Salmonella swiftly boosts the expression of SPI-1 structural components, preparing for infection." (PMID 41188240, 2025). "Our investigation into the regulatory dynamics of virulence genes revealed that ΔsanA exhibited significantly higher expression of sicA, a key SPI-1 component, under conditions that mimic the early stages of infection." (PMID 40304475, 2025). "To further validate the physiological relevance of our in vitro infection cycle model, we assessed the expression of sipA and ssaC, representative virulence genes from SPI-1 and SPI-2, respectively." (PMID 40985779, 2025). "GM-2 and GM-3 were predominantly associated with columnar epithelial responses and included regulators such as ATF2, CDX2, FOXJ2, and AHR, with infection-induced up-regulation of TFs such as SPI1, ESRRA, RFX1, and RARA." (PMID 41042872, 2025). "In contrast, certain other SPI-1 genes, such as avrA and iacP, were maximally expressed between 2–4 h post infection." (PMID 41188240, 2025). "The integration of SPI-1 and SPI-2-encoded genes alongside other virulence determinants equips these strains to adapt to diverse environments and persistently sustain infection, thus emphasizing their significant public health threat." (PMID 40293991, 2025). "This heightened SPI-1 expression, however, imposes a fitness cost, as observed in CI experiments where WT strains outcompeted ΔsanA in the mice infection model." (PMID 40304475, 2025).
infection (continued). "In contrast, the SPI-1/2 mutant preserved immune cell viability throughout infection, underscoring the essential role of the T3SS in mediating inflammasome-driven killing of both neutrophils and macrophages." (PMID 41360763, 2025). "Along the whole infections, ΔSPI-1 was impaired in its ability to invade, generate lesions, and therefore spread, which confirms the role of SPI-1 effectors for the invasion and induction of inflammation." (PMID 37490241, 2024). "Yet, research to date has been limited to SPI-1-related secretion and early timepoints in infection." (PMID 38673776, 2024). "Our findings provide new insight into the mechanisms regulating PM homeostasis in mammalian cells and how the cooperative actions of SPI-1 T3SS effectors subvert membrane trafficking during infection." (PMID 38600106, 2024). "SPI-1 primarily facilitates the initial invasion of the intestinal epithelial cells by the bacterium and is most active during the early phase of infection." (PMID 39335264, 2024). "During infection, Rof blocks Rho binding with rut site and inhibits Rho-dependent termination, leading to displacement of H-NS from SPI-1 locus, continued transcription of virulence genes, and successful host invasion." (PMID 38622116, 2024). "The SPI-1 is required during the intestinal phase of infection, delivering the effector proteins necessary for intestinal invasion and inflammation inside the host cells." (PMID 39462402, 2024). "Together, these data suggest that although exocyst subunits reside in different cellular compartments prior to infection, SPI-1 T3SS effectors act cooperatively to recruit and assemble the exocyst complex at STm invasion sites." (PMID 38600106, 2024). "In particular, we will focus on the Salmonella pathogenicity island (SPI)-1 mediated infection, because it is the most commonly investigated mode of infection." (PMID 36902088, 2023). "Increased SCFAs can directly reduce virulence factors of pathogens, such as acylation of Salmonella pathogenicity island-1 (SPI-1), and thus attenuates infection." (PMID 36656870, 2023). "Although both SPI-1 and SPI-2 contain pro-inflammatory and anti-inflammatory effectors, we found that the entire SPI-1 or SPI-2 exhibited a pro-inflammatory phenotype during infection of macrophages and mice." (PMID 37325511, 2023). "In this study, we investigated the roles of the S. Typhi type 3 secretion systems (T3SSs) encoded on Salmonella pathogenicity islands (SPI)-1 (T3SS-1) and SPI-2 (T3SS-2) during human macrophage infection." (PMID 37341487, 2023). "SPI-1 and SPI-2 encoded the Type 3 secretion system (T3SS) associated with host cell invasion and intracellular survival, key functions for human infection." (PMID 36386628, 2022). "Infection of the transformed MEFs with a NTS T3SS mutant ΔprgH abolished the observed increased host cell adherence and increased host cell infection, indicating that a functional SPI1 T3SS remains required to infect the transformed MEFs." (PMID 36543099, 2022). "This is best illustrated by the fact that, in the mouse model of infection, an orally administered SPI-1 mutant is attenuated but fully virulent if injected intraperitoneally." (PMID 35127930, 2022). "While SPI-1 is mainly involved in the initiating stage of infection, SPI-2 is required for systemic infection by easing the replication of intracellular bacteria within SCV." (PMID 35631023, 2022). "The development of ex vivo infection systems using cultured HeLa cells and the discovery of Salmonella pathogenicity islands 1 (SPI-1) and 2 (SPI-2) have been essential in this respect." (PMID 35127930, 2022). "HilA has been widely reported to have a direct activation effect on two promoters of SPI-1, which plays a critical role in Salmonella invasion during the early stage of infection." (PMID 35955615, 2022).